ATF5 (activating transcription factor 5)
Diseases named in the same sentence as ATF5 in open-access papers (continued):
Sharing a sentence is not in itself a finding about the gene and the disease.
cancer (continued). "ATF5 is a key regulator of the UPRmt in mammals and is involved in the tumorigenesis of a variety of cancers." (PMID 39261452, 2024). "ATF5, a retrograde signaling molecule, is overexpressed during UPRmt activation and contributes to cancer cell invasiveness by inducing integrin expression and maintaining OxPhos function." (PMID 39771153, 2024). "As reviewed above, multiple studies indicate that directly depleting ATF5 in cancer cells suppresses their growth and survival." (PMID 36831248, 2023). "It was demonstrated that ATF5 was upregulated in a wide range of cancers, such as lung cancer, pancreatic cancer, and carcinomas, including ovarian cancer, rectal cancer, leukemia, neural tumors, esophageal cancer, or astrocytoma." (PMID 36674998, 2023). "Following the initial work that suggested a potential role for ATF5 in brain and other cancers, a variety of studies and approaches have provided support for the concept that ATF5 is a target for treatment of malignancies of the brain and other organs." (PMID 36831248, 2023). "As we continue to understand the specific roles of ATF5 and other members of UPRmt in cancer, we become better equipped to develop pharmacological agents that can target UPRmt as a novel form of cancer therapy." (PMID 35864539, 2022). "Taken together, ATF5 is a prospective target for cancer therapy and a prognostic biomarker that has various functions, including promoting tumorigenesis, tumor invasion, and radioresistance." (PMID 35806136, 2022). "Accumulating evidence demonstrates that ATF5 plays an oncogenic role in cancer by regulating gene expressions involved in tumorigenesis and tumor survival." (PMID 35806136, 2022). "The following sections will discuss the known cancer-specific roles of ATF5 and key UPRmt proteins downstream of ATF5: HSP60, HSP10, mtHSP70, LONP1, and ClpP." (PMID 35864539, 2022). "This review explores in detail the regulation of ATF5 expression and signaling pathways and elucidates the role of ATF5 in cancer biology." (PMID 35806136, 2022). "Previous studies have shown that ATF5 expression is significantly upregulated in a variety of cancers, such as epithelial ovarian cancer, glioblastoma, pancreatic cancer and chronic myeloid leukemia." (PMID 35180892, 2022). "Activated ATF5 triggers the transcription of mTOR, a negative regulator of autophagy, inhibiting autophagy in cancer cells." (PMID 35180892, 2022). "In these cancers, ATF5 is an attractive target for cancer therapy because of its crucial role in cell differentiation, tissue development, and cellular stress responses that promote cancer survival." (PMID 35806136, 2022). "Cancer cells utilize signaling molecules and transcriptional products in the UPRmt, such as ATF5, HSP60 and ClpP, to promote their proliferation, growth, invasion and metastasis." (PMID 35180892, 2022). "ATF5 also has a critical role in regulating tissue development, cellular differentiation, and stress responses, and has a promotive role in cancer survival." (PMID 35806136, 2022). "In light of this, we believe that mitochondrial dysfunction in cancer produces a state of chronic mitochondrial stress, which then constitutively activates ATF5 and upregulates the expression of the UPRmt components." (PMID 35864539, 2022). "There are pieces of evidence that link the role of ATF5 in mitochondrial dysfunction in cancer progression." (PMID 34249670, 2021). "In the past, we developed the strategy of generating an inducible or cell-penetrating dominant-negative (dn) peptide form of ATF5 for cancer treatment." (PMID 34065488, 2021). "In ESCC cell lines, we examined all AP-1 transcription factors including JUN, FOS, MAF, and ATF family members and found that FOSL1, MAFK, BATF, and ATF5 are upregulated compared to non-cancer cells." (PMID 34722266, 2021). "ATF5 expression suppression sensitizes cancer cells to anchorage-dependent death signals, while LGALS4 induction recovers cell-cell junctions." (PMID 34249670, 2021).
cancer (continued). "Here, we first found ATF5 was dramatically upregulated in ESCA cancer and related with poor survival time." (PMID 33980247, 2021). "Past studies have implicated ATF5, CEBPB and CEBPD in the regulation of cancer cell responsiveness to the microtubule-targeting drug Taxol (paclitaxel), which is used to treat breast and other tumor types." (PMID 34065488, 2021). "With the here-reported regulation of DKK1 expression, ATF5 becomes further involved in the modulation of Wnt/β-catenin-mediated target gene expression, and thus cancer progression and metastasis also for CRC." (PMID 35008201, 2021). "ATF5, as a transcription factor, functions as an oncogenic role in enhancing cell survival, migration and radioresistance of cancer cells." (PMID 34895217, 2021). "The resulting cell-penetrating dn peptide for ATF5, CP-dn-ATF5, inhibits survival/growth of a wide variety of cultured tumor cell types and blocks or slows tumor growth and prolongs survival in multiple mouse cancer models." (PMID 34065488, 2021). "ASNS, the gene encoding asparagine synthetase, has been reported as a direct target of ATF5 and CEBPB, and its over-expression is associated with cancer cell proliferation, metastasis and therapeutic resistance." (PMID 34065488, 2021). "Activating transcription factor 5 (ATF5) is well-known for its role in transcriptional activation of various genes, which in turn promotes the progression of various forms of cancer." (PMID 33980247, 2021). "Upregulation of HSP60 and ATF5 during UPRmt predominantly increases the carcinoma cell’s survival threshold and promotes tumor progression, therapeutic resistance, and resistance towards apoptosis." (PMID 34717757, 2021). "Activating transcription factor 5 (ATF5) is upregulated under diverse stress conditions and is overexpressed in a variety of cancers." (PMID 32603335, 2020). "Further, ATF5 is upregulated in a variety of carcinomas and is a survival factor in several cancer cell lines." (PMID 32603335, 2020). "Taken together, these findings suggest miR-520b-3p to be an important and novel contributor to the modulation of ATF5 expression under diverse stress conditions and across different cancer cell types." (PMID 32603335, 2020). "Further studies are warranted to investigate the potential utility of miR-520b-3p as a therapeutic agent to re-sensitize cancer cells to chemotherapeutics as well as impact tumor growth via reversal of ATF5 expression in cancer cells." (PMID 32603335, 2020). "The purpose of the present study was to investigate miRNA regulation at the 3’ untranslated region (UTR) of ATF5, with the goal of demonstrating a reversal of the upregulation of ATF5 induced under diverse cellular stress in cancer cells." (PMID 32603335, 2020). "Taken together, these findings support the idea that dn-ATF5 promotes caspase-dependent apoptotic death of cancer cells and that it does so by multiple pro-apoptotic actions including downregulation of survivin and BCL2." (PMID 31551409, 2019). "The transcription factor ATF5 is over-expressed in a variety of cancer types and such over-expression correlates with poor prognosis and treatment resistance." (PMID 31551409, 2019). "Given survivin’s roles in cancer cell proliferation, survival, metastasis, and therapeutic resistance, dn-ATF5-induced survivin depletion is highly likely to contribute to dn-ATF5’s anti-tumor actions." (PMID 31551409, 2019). "This suggests that dn-ATF5 triggers pro-apoptotic events in addition to survivin depletion that are sufficient to kill cancer cells." (PMID 31551409, 2019). "The critical role for ATF5 in the development of various cancer types has led to preclinical evaluation of several methods to target ATF5 and has yielded promising results." (PMID 29137451, 2017). "This suggests an oncogenic role for ATF5 in these cancer types where overexpression is seen in malignant tissues." (PMID 29137451, 2017).
cancer (continued). "Dysregulation of ATF5 expression is commonly observed in a variety of different cancer types such as those of the brain, lung, and pancreas." (PMID 29137451, 2017). "The literature discussed in this review provides a foundation for the functional role of ATF5 in the context of cellular differentiation, stress, and cancer." (PMID 29137451, 2017). "Our previous work has demonstrated that ATF5 is a key factor for cancer-specific cell survival and it is highly expressed in U87 cell." (PMID 28473657, 2017). "As most of the mechanistic studies involved with the prosuvival function of ATF5 were done in cancer cells, the mechanism with which ATF5 mediates a prosurvival effect in normal tissues remains to be characterized." (PMID 29137451, 2017). "This reveals an important post-translational mechanism with which cancer cells can aberrantly upregulate ATF5 activity by increasing the half-life of ATF5." (PMID 29137451, 2017). "While a body of literature already exists around the role of ATF5 in cancer biology, notably in the regulation of apoptosis, it will be interesting to further investigate the role of ATF5 in the context of the UPRmt and cancer." (PMID 28798902, 2017). "As mentioned in the previous section on the role of ATF5 in cancer development, ATF5 possesses numerous properties that make it an attractive target for cancer treatment." (PMID 29137451, 2017). "Since then, ATF5 became a gene of interest and reports of its expression and its role in promoting the survival of various stress-induced cancer cells have been published." (PMID 28785242, 2017). "Activating transcription factor-5 (ATF5) is an anti-apoptotic factor and has been implicated in enhancing the survival of cancer cells under stress and in regulating the autophagy process." (PMID 28785242, 2017). "In this study, we showed that ATF5 enhances both radioresistance and malignant phenotypes in cancer cells." (PMID 25682872, 2015). "We illustrated the concept in this study by showing that ATF5 induces both radioresistance and malignancy in cancer cells." (PMID 25682872, 2015). "Here, we show that activating transcription factor 5 (ATF5) promotes radioresistance and malignancy in cancer cells after irradiation." (PMID 25682872, 2015). "In the G1-S phase of the cell cycle, cancer cells express high levels of ATF5, which promotes cell cycle progression and thereby increases radioresistance." (PMID 25682872, 2015). "In this study, we demonstrated that ATF5 enhances both radioresistance and malignancy in cancer cells after irradiation." (PMID 25682872, 2015). "We also showed that A549 cells that survive irradiation express high levels of ATF5, which enhances malignant phenotypes such as tumorigenesis, growth, and invasiveness in cancer cells." (PMID 25682872, 2015). "From the results in this study, we suggest that ATF5 is a key regulator of cancer recurrence correlated with poor prognosis after radiotherapy." (PMID 25682872, 2015). "We suggest that ATF5 is a possible therapeutic target for the treatment of malignant tumors in combination with radiotherapy." (PMID 25682872, 2015). "In this perspective, we summarize recent advances in ATF5 research, focusing on its role in promoting cancer and its potential as a target for cancer therapy." (PMID 21311102, 2010). "In summary, here, we reveal mechanotransduction pathways involving ATF5 in cancer cells." (PMID 40124511, 2025). "Thus, our findings suggest that stiff ECMs activate ATF5 in cancer tissues and promote cancer progression by driving cell proliferation." (PMID 40124511, 2025). "Therefore, it is suggested that stiff ECMs induce the nuclear localization of ATF5 via active protein transport in cancer cells." (PMID 40124511, 2025). "Therefore, we treated cancer cells with inhibitors of actomyosin and adhesion molecules, and then analyzed ATF5 localization, EGR1 expression, JAK phosphorylation, and MYC expression." (PMID 40124511, 2025).
cancer (continued). "Additionally, it was identified that the elevated level of ATF5 is found in a variety of cancers, including thyroid follicular lymphoma, epithelial ovarian carcinoma, colorectal adenocarcinoma, breast carcinoma, pancreatic cancer, and malignant glioma." (PMID 40943612, 2025). "In cancer, ATF5 and HSF1, which are both involved in the UPRmt, have been linked to oncogenesis." (PMID 40680837, 2025). "Our findings are limited to the context of specific cancer cells; therefore, whether ATF5 is activated by stiff ECMs or is critical for proliferation in other cells, including normal and cancer cells, should be elucidated in the future." (PMID 40124511, 2025). "ATF5 is dramatically overexpressed and correlated with poorer prognosis in many cancer patients." (PMID 39261452, 2024). "ATF5, Hsp60, mtHsp70, Lonp1, and Clpp are upregulated in cancer, favoring tumor growth." (PMID 38882057, 2024). "Furthermore, ATF5 activation produced resistance to radiotherapy and increased the invasiveness of cancer cells." (PMID 36674998, 2023). "Thus, like CP-dn-ATF5, Bpep and Dpep show both efficacy and apparent safety in animal cancer models." (PMID 36831248, 2023). "Specifically, the mechanism by which ATF5 regulates UPRmt in cancer must be further addressed." (PMID 35864539, 2022). "miR-520b-3p can suppress ATF5 expression levels and play a positive role in tumor inhibition during diverse stress conditions in ATF5-oncogenic cancer cells; however, the specific mechanisms of miR-520b-3p-induced ATF5 inhibition are not fully understood and require further investigation." (PMID 35806136, 2022). "As a transcription factor, ATF5 regulates the expression of various anti-apoptotic genes in cancer." (PMID 35864539, 2022). "Furthermore, recent studies have also revealed the protective role of ATF5 in mammalian mitochondrial dysfunction and its relation to cancer development." (PMID 35806136, 2022). "Targeting ATF5 is a potential strategy to kill cancer cells." (PMID 35180892, 2022). "Furthermore, an overview of putative therapeutic strategies that can be used for restoring aberrant ATF5 activity in different cancer types is provided." (PMID 35806136, 2022). "Additionally, ATF5-induced upregulation of integrin-α2 and integrin-β1 is conducive to cancer cell invasion." (PMID 35180892, 2022). "Additionally, recent studies have revealed that ATF5 is a potential therapeutic target for many other cancers." (PMID 35806136, 2022). "Notably, upregulation of HSP60 expression and its upstream regulator ATF5 has been shown to enhance the apoptotic threshold in cancer cells resulting in therapeutic resistance in many cancer types." (PMID 34630117, 2021). "Many studies have examined the effectiveness of anti-ATF5 in cancer treatment." (PMID 33980247, 2021). "In various cancers, the ATF5 locus on chromosome 19q13.33 is generally amplified." (PMID 34895217, 2021). "GSEA analysis was conducted to further assess the potential biological roles of ATF5 in cancers." (PMID 34895217, 2021). "Although the role of UPRmt in radio-resistance in cancer cells remains unclear, ATF5 has been known to increase radio-resistance in some cancer cells." (PMID 33640883, 2021). "Besides, ATF5 plays a vital role in tumorigenesis of several cancers, including breast cancer, lung cancer, ovarian cancer, pancreatic cancer, rectal cancer, renal cell cancer, hepatocellular cancer." (PMID 33980247, 2021). "It has been hypothesized that dysregulation of ATF5 may serve as a survival factor in cancer development, notably gliomagenesis." (PMID 32415090, 2020). "It follows that ATF5 is a potential target for cancer therapy, and a better understanding of its regulation could lead to enhanced or novel therapeutics for cancer treatment." (PMID 32603335, 2020). "As ATF5 is a stress responsive transcription factor, this could have ramifications in the treatment of a number of stress-related diseases, particularly cancer and cancer therapy resistance." (PMID 32603335, 2020).
cancer (continued). "Supporting the relevance of our findings that exogenously introduced miR-520b-3p reverses the upregulation of ATF5 protein expression in cancer cells under stress, we report a significant decrease in endogenous miR-520b-3p levels in HeLa cells exposed to both ER stress and amino acid deprivation." (PMID 32603335, 2020). "Activating transcription factor 5 (ATF5) enhances radioresistance and malignancy in cancer cells." (PMID 33322792, 2020). "REG3G, ACAT2, and ATF5 have also been found in various cancers." (PMID 31148949, 2019). "As a new member of ATF/CREB family ATf5 can promote cancer cells survival specifically." (PMID 28473657, 2017). "In addition, ATF5 is overexpressed in several cancer cells, including glioma cells and breast cancer cells, and regulates cancer cell survival." (PMID 28744205, 2017). "Furthermore, we will discuss how the prosurvival role of ATF5 aides in cancer development, followed by current advances in targeting ATF5 using dominant-negative biologics, and perspectives on future research." (PMID 29137451, 2017). "Future preclinical and clinical research will help reveal whether ATF5 is indeed a viable target for clinical cancer therapy." (PMID 29137451, 2017). "These functions in tissue development, i.e. regulating the growth and differentiation of stem and progenitor cells, also supports the notion that ATF5 activity may play a role in the self-renewal and differentiation of cancer stem cells." (PMID 29137451, 2017). "While this research provides a novel function for ATF5 in cellular stress responses, it imposes further curiosity whether the UPRmt processes mediated by ATF5 can contribute to cancer development in ATF5-dysregulated cancers." (PMID 29137451, 2017). "Furthermore, ATF5 increases malignant phenotypes, such as cell growth and invasiveness, in cancer cells in vitro and in vivo." (PMID 25682872, 2015). "In G2-M phases, cancer cells are radiosensitive because they express low levels of ATF5." (PMID 25682872, 2015). "Therefore, in this study, we investigated the role of ATF5 in radioresistance and in the development of malignant phenotypes in human cancer cells after irradiation." (PMID 25682872, 2015). "In this study, we showed that ATF5 promotes radioresistance and malignancy in cancer cells." (PMID 25682872, 2015). "We showed that ATF5 perturbs MRLC phosphorylation in cancer cells." (PMID 25682872, 2015). "A pair of studies has provided intriguing evidence that high ATF5 expression levels may correlate with poor prognosis in cancer patients." (PMID 21311102, 2010). "ATF5 is also highly expressed in a variety of other cancers, and preliminary studies have shown that the ATF5-mediated survival pathway is active in diverse human cancer cell lines." (PMID 21311102, 2010). "Identification of additional ATF5 target genes would further define the important role of ATF5 in cancer development, and may also identify additional potential therapeutic targets." (PMID 21311102, 2010). "Taken together these studies demonstrate that ATF5 mediates cell survival in many cancers, and suggest that inhibition of the ATF5-mediated survival pathway may have therapeutic implications for the treatment of a wide range of malignancies." (PMID 21311102, 2010). "Hence, gain of the genes in apoptosis, including the anti-apoptosis genes BIRC2, BIRC3, and ATF5, can help carcinoma cells to evade apoptosis." (PMID 19911042, 2009). "Moreover, although ATF5 expression in normal tissues is lower than that in cancer tissues, there may be a function of ATF5 in corresponding normal tissues, such as the epithelial tissues of the pancreas and lungs." (PMID 40124511, 2025). "Recent studies have also revealed that ATF5 increases the radiation resistance of cancer cells by promoting cell cycle progression, cell growth, and invasiveness, indicating that it may reduce the effects of radiation therapy; perhaps using ATF5 antagonists may prevent this." (PMID 35806136, 2022).